SCARNA1 (small Cajal body-specific RNA 1)
Synonyms: ACA35
Gene: Small Cajal body-specific RNA gene on chromosome 1 (27,834,401 to 27,834,566, forward strand). Ensembl gene ENSG00000252947.
Gene Ontology:
Biological process: RNA processing
Cellular component: Cajal body; nucleolus
Homologues: Orthologues: chimpanzee SCARNA1 (99% identical), macaque SCARNA1 (97% identical), rabbit SCARNA1 (93% identical), guinea pig SCARNA1 (89% identical).